ARG1 (arginase 1)
Diseases named in the same sentence as ARG1 in open-access papers (continued):
Sharing a sentence is not in itself a finding about the gene and the disease.
schistosomiasis (14 papers, 2008 to 2025). An infectious disease caused by parasitic trematodes of the genus Schistosoma that colonize human blood vessels and release eggs that can cause granulomatous reactions leading to acute (swimmer's itch or acute schistosomiasis syndrome) or chronic disease. "The development of fibrosis in schistosomiasis is dependent on Th2 cytokines, and mice deficient in IL-4/IL-13 fail to upregulate Arg1." (PMID 19360123, 2009). "Instead, the conditional deletion of Arg1 in macrophages caused a significant exacerbation of schistosomiasis." (PMID 19360123, 2009). "In schistosomiasis-induced fibrosis models, ARG1 deletion led to an increase in type 2 inflammation and consequently increased fibrosis because of an accumulation of arginine, which supports CD4+ T cell proliferation." (PMID 40875483, 2025). "The expression of M2 macrophage markers such as Arg-1, Ym-1, and Fizz-1 were highly increased in schistosomiasis." (PMID 29094025, 2017). "It had been confirmed that Th1 immunity, CAMs, and expression of NOS-2 correlate with acute mortality in schistosomiasis, while Th2 cytokine, AAMs activation, and Arg-1 expression correspond to fibrogenesis." (PMID 27875565, 2016). "Our findings also demonstrate how quickly this immature Lyz2lo macrophage population can become alternatively activated with high expression of Arg1, which we have shown critically controls the pathogenesis of fibrosis in schistosomiasis." (PMID 25211233, 2014). "To investigate the role of Arg1+ AAMs in Th2-mediated lung pathology, we recreated, standardized, and synchronized this feature of schistosomiasis by intravenously injecting a single dose of live parasite eggs into egg-sensitized mice." (PMID 23637937, 2013). "Instead of promoting Th2 disease, our data suggest that macrophage-specific Arg1 contributes to the resolution of schistosomiasis by inhibiting CD4+ T cell effector function." (PMID 19360123, 2009). "In schistosomiasis, Ly6Chi monocytes in granulomas respond to Th2-cell derived IL-4 and IL-13 to exhibit an arginase 1-positive, resistin-like molecule alpha-positive and chitinase-like 3-positive M2 phenotype or an alternatively activated macrophage (AAM) phenotype." (PMID 31194740, 2019). "Nevertheless, although Arg1 expression is associated with Th2-dependent fibrosis, the contribution of macrophage-specific Arg1 to the pathogenesis of fibrosis in schistosomiasis was unknown." (PMID 19360123, 2009). "The arginase 1-expressing AAM population suppresses Th2 cytokine-driven inflammation and fibrosis in schistosomiasis." (PMID 31194740, 2019). "We show that in response to IL-4 and IL-13, Lyz2loIL-4Rα+ macrophages differentiate into an arginase 1-expressing alternatively-activated macrophage (AAM) population, which slows the development of lethal fibrosis in schistosomiasis." (PMID 25211233, 2014). "Moreover, the F4/80+ cells also showed co-expression of Arg-1 or CD206, which indicated that the infiltrated F4/80+ macrophages exhibited the M2-polarized phenotype in the murine schistosomiasis model." (PMID 27875565, 2016). "Most notably, Arg1 mRNA was not reduced, yet Arg1 expression in macrophages is predominantly driven by an IL-4Rα/STAT6-dependent mechanism in schistosomiasis." (PMID 25211233, 2014). "In contrast to Arg1’s role in the liver and small intestine during schistosomiasis, we could not detect any distinctions between the lungs of WT and Arg1 KO mice acutely challenged with the same eggs and egg antigens." (PMID 23637937, 2013). "Strikingly, in contrast to the findings with Il4ra−/flox;LysMcre mice, our data suggest that Arg1-expressing AAMs are not required to suppress acute Th1/NOS2/LPS-mediated morbidity and mortality in schistosomiasis." (PMID 19360123, 2009).
urea cycle disorder (14 papers, 2012 to 2026). A genetic inborn error of metabolism characterized by the deficiency of one of the enzymes necessary for the urea cycle. "Arginase 1 deficiency (ARG1-D) is a rare hereditary urea cycle disorder characterized by elevated arginine levels, resulting in progressive neurological impairment and severe physical and cognitive disability." (PMID 40237972, 2025). "Data set from NBS in the United States and the Urea Cycle Disorders Consortium suggested that the birth prevalence of ARG1 deficiency is about 1 in 1,000,000 live births." (PMID 39669610, 2024). "ARG1 deficiency is a rare urea cycle disorder (UCD), and its frequency is estimated to be 1 per 2,200,000 births in Japan." (PMID 34646736, 2021). "Arginase 1 (ARG1) deficiency is a rare urea cycle disorder (UCD), with an estimated frequency of 1 per 2,200,000 births in Japan." (PMID 34646736, 2021). "Urea cycle disorders are rare; arginase-1 deficiency is one of those extremely rare autosomal recessive metabolic disorders." (PMID 32025996, 2019). "Symptoms developed in ARG1-deficiency human patients are generally less severe compared to other urea cycle disorders." (PMID 24224027, 2013). "The clinical manifestations of arginase 1 deficiency are different from other urea cycle disorders." (PMID 32769929, 2020). "Hyperargininemia is an extremely rare autosomal recessive condition that is associated with urea cycle disorder (UCD); it is caused by a deficiency of arginase 1, which hydrolyzes arginine to form ornithine and urea." (PMID 33542202, 2021). "Arginase 1 deficiency (ARG1-D) is a rare hereditary metabolic disorder within the urea cycle disorder (UCD) group, caused by mutations in the ARG1 gene." (PMID 40237972, 2025). "Arginase 1 deficiency (ARG1‐D), a distinct urea cycle disorder (UCD), is a debilitating, progressive, inherited metabolic disease characterized by persistent elevation of plasma arginine, and is associated with considerable morbidity and early mortality." (PMID 35822089, 2022). "Arginase 1 deficiency (ARG1‐D) is a rare, progressive and debilitating urea cycle disorder characterized by clinical manifestations including spasticity, seizures, developmental delay, and intellectual disability." (PMID 35822089, 2022). "Our studies provide proof-of-concept for gene-editing at the Arg1 locus and highlight the challenges that lie ahead to restore sufficient liver-based urea cycle function in patients with urea cycle disorders." (PMID 28566761, 2017). "In contrast, spastic paraplegia is found only in arginase-1 deficiency and is not seen in other urea cycle disorders." (PMID 32025996, 2019).
autoimmune disease (12 papers, 2017 to 2025). A disorder resulting from loss of function or tissue destruction of an organ or multiple organs, arising from humoral or cellular immune responses of the individual to their own tissue constituents. "Previously, immunosuppressive subsets of neutrophils have been identified in human peripheral blood in autoimmune diseases and cancer, as well as the release of enzymatic or chemical mediators such as arginase-1 or ROS." (PMID 40182847, 2025). "As described, myeloid‐derived suppressor cells—particularly the polymorphonuclear subset (PMN‐MDSCs)—act to facilitate immune cell senescence in part through enhanced Arg1 production, primarily described in relation to either cancer or autoimmune disease." (PMID 31793661, 2021). "Similarly, the levels of Arg-1 and IL-1β were positively correlated with the percentage of MDSCs and Th17-mediated autoimmune diseases." (PMID 37733169, 2024). "In humans, ARG1 exists in the granulocyte granular compartment of healthy subjects, the peripheral blood mononuclear cells of patients after injury, and the activated monocytes of patients with autoimmune diseases." (PMID 36918848, 2023). "At present, it is unknown how inhibition of IGF-1R by linsitinib mediates upregulation of arginase-1 in the context of an autoimmune disorder in the bone marrow." (PMID 37810891, 2023). "While IL-17 is a strong proinflammatory cytokine associated with host defense against bacterial and fungal infections and is also elevated in several autoimmune diseases, IL-5/IL-13 and Arg1-positive M2 macrophages are part of the anti-inflammatory type 2 (Th2) immunity." (PMID 28680858, 2017). "MDSCs derived from various pathological conditions (such as cancer, inflammation and autoimmune diseases) can inhibit specific antitumor immunity mediated by T cells and natural antitumor immunity mediated by NK cells and macrophages by expressing high levels of ARG-1, INOS and ROS." (PMID 35725835, 2023). "Moreover, ARG1 has been shown to be upregulated in autoimmune disease such as rheumatoid arthritis." (PMID 34480465, 2022). "Indoleamine-2,3-dioxygenase 1 (IDO1), Arginase 1 (ARG1), the main catabolizing enzymes in tryptophan and arginine metabolism are studied in autoimmune diseases." (PMID 32341806, 2020). "However, in a proinflammatory environment, as observed in a mouse model of autoimmune disease, primary biliary cholangitis, Man impairs the production of TNF‐α, IL‐1β, Arg1, and IL‐6 cytokines." (PMID 39950558, 2025).
Arthritis (11 papers, 2013 to 2025). Inflammation of a joint. "L-arginine supplementation restrains inflammatory bone loss in experimental mouse arthritis and inhibits osteoclastogenesis in an ARG1-dependent manner tilting energy metabolism of inflammatory osteoclasts from glycolysis to oxidative phosphorylation." (PMID 39863828, 2025). "c-Jun differentially regulates cyclooxygenase-2 (COX-2) and arginase-1 (ARG-1) and promotes macrophage activation, thus contributing to arthritis progression." (PMID 37457726, 2023). "A recent study reported that the subunit of AP-1 transcription factor c-Jun promotes arthritis in macrophages by regulating cyclooxygenase-2 and arginase-1 expression." (PMID 32290250, 2020). "The majority of M2 markers (IL-1RII, CD163, CD206, Arg1 and Ym1) were also somewhat upregulated during the course of arthritis, although in lesser extent than the M1 markers, with the exception of Arg1 and Ym1 which were especially high at day 1 after induction of AIA." (PMID 23468840, 2013). "Conversely, arginine depletion by application of recombinant ARG1 also inhibits RANKL-driven osteoclastogenesis and ameliorates arthritis in mice." (PMID 39863828, 2025). "Our previously studies demonstrated that Arg-1 secreted by MDSC facilitates TH17 cell polarization in SLE patients and patients with arthritis." (PMID 32391010, 2020). "We demonstrated that Arg-1 and IL-1β secreted by MDSC drive TH17 cell differentiation in mouse models and patients with systemic lupus erythematosus (SLE) and arthritis." (PMID 32391010, 2020). "Our previously study showed that Arg-1 secreted by MDSC facilitates TH17 cell polarization in SLE patients and patients with arthritis." (PMID 32391010, 2020). "Furthermore, in an arthritis model, LPS‐induced FOSL1 was shown to directly bind to the Arginase 1 (Arg1) promoter, inhibiting its transcription and promoting macrophage polarization toward the proinflammatory M1 phenotype." (PMID 41446762, 2025). "In the arthritis model, Fra-1 expression was up-regulated after LPS activated Toll-like receptors (TLR) cascade, and then it was directly bound to the promoter region of Arginase 1 (Arg1) to inhibit its transcription, making macrophages transform into M1 pro-inflammatory phenotype." (PMID 36032067, 2022).
Cerebral ischemia (11 papers, 2018 to 2025). Restriction of arterial blood supply to the brain associated with insufficient oxygenation to support the metabolic requirements of the tissue. "Arg1 has, for example, been associated with improved outcomes in cerebral ischemia and spinal cord injury." (PMID 41488750, 2025). "Focusing on the role of Arg1+ microglia/macrophages in cerebral ischemia, we depleted Arg1+ microglia/macrophages with selective inhibitors MCLs." (PMID 36361836, 2022). "Previous studies have shown that Arg1 expression was upregulated in focal areas after cerebral ischemia, especially in inflammatory cells." (PMID 36361836, 2022). "However, after cerebral ischemia, a subset of microglia and macrophages upregulates Arg-1 expression." (PMID 38075277, 2023). "Therefore, the effect of Arg1+ microglia/macrophages on cerebral ischemia may be even underestimated." (PMID 36361836, 2022). "Anti-inflammation related genes Arginase 1 (Arg1) and Chitinase-like 3 (Ym1) peaked at D1 while IL-10, Transforming growth factor β (TGF-β) and CD206, which were induced at 1 day after cerebral ischemia, peaked by 7 to 14 days." (PMID 29896414, 2018). "In the current study, we showed that TOPK expression after cerebral ischemia-reperfusion followed a similar pattern to that of the M2 surface markers CD206 and Arg1." (PMID 29896413, 2018). "In addition, it has been reported that 25HC protects against cerebral ischemia–reperfusion injury by inhibiting STING activity, and that STING activation is negatively correlated with ARG1 expression." (PMID 41020041, 2025). "We found that Vefgc gene delivery increased the immunoreactivity of M2a-like microglia and M2a-macrophages after brain ischemia without altering the total amount of microglia or macrophages, detected in the perifocal area by Arg1 and Iba1-immunolabelling, respectively." (PMID 38822994, 2025). "For CD206 and Arg-1, cerebral ischemia injury did not elevate their gene expression levels." (PMID 36317102, 2022).
cholangiocarcinoma (11 papers, 2012 to 2026). A carcinoma that arises from the intrahepatic biliary tree (intrahepatic cholangiocarcinoma) or from the junction, or adjacent to the junction, of the right and left hepatic ducts (hilar cholangiocarcinoma). "Immunohistochemistry for hepatocytic markers arginase-1 and HepaPar1 is useful in this regard, whereas cytokeratin 7 is positive in most scirrhous HCCs and almost all cholangiocarcinomas." (PMID 35954333, 2022). "It seems possible that a variable interpretation of such findings has contributed to the high variability of published data on arginase-1 positivity in cholangiocarcinoma, ranging from 0% to 68%." (PMID 34943588, 2021). "Other tumor entities with occasional and mostly low-level arginase-1 immunostaining included clear cell carcinomas of the ovary, neuroendocrine tumors of the pancreas, mucinous and lobular carcinoma of the breast, cholangiocarcinoma, and colorectal adenocarcinoma." (PMID 34943588, 2021). "We found that macrophages stimulated with the supernatant of cholangiocarcinoma cells expressed high levels of M2 markers, including CD163, CD206, ARG-1, and IL-10." (PMID 39256888, 2024). "Third, due to the low expression of Arg-1 and GPC-3 in cholangiocarcinoma tissues, the sample size was small." (PMID 34715880, 2021). "The present study examined arginase-1 and HepPar-1 expression in 50 HCC cases, 38 cases of metastatic carcinomas to the liver from varying sites, 12 cases of cholangiocarcinoma and 10 specimens of normal liver tissues." (PMID 23111165, 2012). "The current study aims to examine the immunohistochemical staining of arginase-1 in cases of HCC, metastatic carcinoma involving the liver and cholangiocarcinoma as compared to HepPar-1 that is conventially used." (PMID 23111165, 2012). "Targeting these metabolic pathways (such as GLS1, ARG1, PHGDH, IDO1, etc.)may restore the function of immune cells, inhibit tumor progression, and provide new strategies for the treatment of cholangiocarcinoma." (PMID 41513616, 2026). "For instance, Arg-1 demonstrates superior sensitivity (85.7%) in poorly differentiated HCC compared to HepPar1 (46.4%), but its occasional reactivity in cholangiocarcinoma (6.9%) necessitates integration with GPC3 (specificity 97.3%) or pCEA (canalicular pattern specificity)." (PMID 40941632, 2025). "If we had disregarded a weak to moderate arginase-1 immunostaining limited to the cytoplasm (non-nuclear) in samples from the liver, we would not have recorded any arginase-1 positivity in cholangiocellular carcinomas." (PMID 34943588, 2021). "Furthermore, the combined use of arginase-1 and HepPar-1 can provide a potentially promising tool to improve the accuracy in distinguishing HCC from metastatic carcinoma and cholangiocarcinoma." (PMID 23111165, 2012). "Therefore; the primary purpose of the current study was to examine the immunohistochemical staining of arginase-1 in cases of HCC, metastatic carcinoma involving the liver and cholangiocarcinoma as compared to HepPar-1." (PMID 23111165, 2012).
head and neck squamous cell carcinoma (11 papers, 2020 to 2024). A squamous cell carcinoma that arises from any of the following anatomic sites: lip and oral cavity, nasal cavity, paranasal sinuses, pharynx, larynx, and salivary glands. "Moreover, Tadalafil was found to reduce activity of iNOS and Arg-1 on both MDSCs and Tregs to disrupt their roles in patients with head/neck squamous cell carcinoma (HNSCC), even though there were low grade of adverse events (such as back pain/myalgia)." (PMID 33613512, 2020). "Phosphorylated STAT3 can directly bind to the ARG1 promoter region of myeloid-derived suppressor cells (MDSCs) in head and neck squamous cell carcinoma (HNSCC) to stimulate transcription and enhance the immunosuppressive properties of MDSCs." (PMID 39051546, 2024). "For example, phosphorylated STAT3 levels in MDSCs isolated from head and neck squamous cell carcinoma (HNSCC) patients positively correlate with ARG1 expression and suppression of autologous T cell proliferation." (PMID 36161514, 2023). "Knockdown of semaphorin 4d (Sema4D) in a human head and neck squamous cell carcinoma (HNSCC) cell line resulted in a loss of MDSC function, as shown by a decrease in the production of the immunosuppressive cytokines arginase-1, TGF-β, and IL-10 by MDSCs." (PMID 37039643, 2023). "This study evaluated Arg-1 protein levels in tumors and the circulation of patients with head and neck squamous cell carcinoma (HNSCC) in relation to clinical stage and prognosis." (PMID 38001706, 2023). "The mRNA level of ARG1 has been demonstrated as an adverse prognostic factor for the OS of head and neck squamous cell carcinoma (HNSCC) patients." (PMID 35242138, 2022). "Treatment with the Arg1 inhibitor nor-NOHA abrogated MDSC-mediated T cell suppression experimentally, and restored the proliferation of MDSC-suppressed lymphocytes from patients with multiple myeloma or head and neck squamous cell carcinoma (HNSCC)." (PMID 38464388, 2024).
lymphoma (11 papers, 2014 to 2024). A malignant (clonal) proliferation of B- lymphocytes or T- lymphocytes which involves the lymph nodes, bone marrow and/or extranodal sites. "Human lymphoma patients with higher IL-10 producing MDSCs (but not Arg1 or iNOS) are associated with reduced anti-tumoural NK cells in blood." (PMID 38464388, 2024). "Thus, MDSCs in lymphoma and multiple myeloma patients were correlated with an upregulated gene expression of ARG-1 and iNOS, and increased expression of ARG-1 in PMN-MDSCs was associated with the disease progression and the resistance to therapy." (PMID 34441758, 2021). "Plasma exosomes from EBV-infected lymphoma cells, which mainly contain BART-miRNAs, function similarly to pro-inflammatory cytokine to trigger the secretion of ARG1, TNF-α, and IL-10 in monocytes and macrophages." (PMID 36411555, 2024). "Activated MDSC express high amounts of arginase-1 and NOS2, and inhibitors of both enzymes (L-NMMA for NOS2 and norNOHA for arginase-1) reversed MDSC suppressive mechanisms in MM and lymphoma models." (PMID 25538893, 2014). "Novel drugs, targeting TME as TGF-β or ARG1 inhibitors, are undergoing clinical trials in cancer patients, but there is a significant lack of trials in lymphoma patients." (PMID 38920685, 2024). "Unfortunately, no clinical trials on arginase-1 inhibitors are currently in progress for lymphomas." (PMID 38920685, 2024). "Activated MDSCs express high amounts of arginase 1 and NOS2, and inhibitors of both enzymes (L-NMMA for NOS2 and nor NOHA for arginase-1) reversed MDSC suppressive mechanisms in MM and lymphoma models." (PMID 31640764, 2019).